IGF1 (insulin like growth factor 1)
Diseases named in the same sentence as IGF1 in open-access papers (continued):
Sharing a sentence is not in itself a finding about the gene and the disease.
cerebrovascular disease (12 papers, 2014 to 2026). "Our findings demonstrate a critical role for VSMCs in IGF-1 deficiency-related cerebrovascular disease and VCID." (PMID 38425784, 2024). "Data from humans and animal models indicate that decreased IGF-1 is associated with worsened cerebrovascular disease and signs of VCID." (PMID 38425784, 2024). "Human studies have also shown that low levels of serum free or total IGF-1 are associated with an increased risk of cardiovascular and cerebrovascular diseases." (PMID 37266131, 2023). "This article reviews the correlation between IGF-1 and cerebrovascular disease and explores the potential relationship and mechanism between IGF-1 and cSVD." (PMID 37358957, 2023). "Meanwhile, we found that higher IGF-1 concentrations were related to lower white matter hyperintensity, suggesting a potential protective role of IGF-1 not only again neurodegeneration, but also against cerebrovascular disease." (PMID 37608387, 2023). "Notably, these benefits occur independently of GH/IGF-1 signaling, highlighting their therapeutic potential for cardiovascular and cerebrovascular diseases." (PMID 42292828, 2026). "IGF-1 is considered as an important growth factor for cardiovascular systems, while lower levels of IGF-1 may contribute to an increase in cardiovascular and cerebrovascular diseases." (PMID 39727499, 2024). "Also, it was shown recently that the IGF-1 pathway has beneficial effect on cardiovascular and cerebrovascular disease." (PMID 32733823, 2020).
colorectal tumor (12 papers, 2009 to 2025). "That study further showed that directly measured serum IGF‐1 levels were associated with increased risk of all colorectal tumor subsites, including proximal colon, distal colon, and rectal cancer." (PMID 32717139, 2020). "Another study showed that serum concentration of IGF1 was higher in allele-A carrying IGF1R rs7166348 polymorphism and associated with a higher risk of colorectal neoplasm." (PMID 37284192, 2023). "IGF-1 is involved in cell cycle progression and is highly expressed in colorectal tumor tissues, indicating that IGF-1 participates in colon carcinogenesis." (PMID 28170448, 2017). "By hierarchical clustering of hub genes using Xena Functional Genomics Explorer, we found that PHLPP2, ACALB, IGF1, and BCL2 were low‐expressed in colorectal tumor tissues." (PMID 33190424, 2021).
mesothelioma (12 papers, 2009 to 2025). A usually malignant and aggressive neoplasm of the mesothelium which is often associated with exposure to asbestos. "Insulin-like growth factor-1 (IGF-1) is part of the IGF-family and is only reported in 3 papers focussing on canine intestinal organoids and 1 paper focussing on canine mesothelioma tumoroids." (PMID 40417361, 2025). "This is particularly interesting in the light of our previous report where exposure of mesothelioma cells to EGF and IGF-1 inhibited expression of syndecan-1 and -2." (PMID 23144729, 2012).
muscular dystrophy (12 papers, 2008 to 2021). Muscular dystrophy (MD) refers to a group of more than 30 genetic diseases characterized by progressive weakness and degeneration of the skeletal muscles that control movement. "Transgenic mice over-expressing IGF-1 have increased muscle mass while mice deficient in IGF-1 have a severe muscular dystrophy." (PMID 21040371, 2011). "The major findings of this study indicate that muscle-specific expression of IGF-1 (mIGF-1) can counter aspects of the muscular dystrophy associated with the loss of dystrophin, modulating relevant molecules of the genetic and epigenetic circuitries in the mdx dystrophic mouse model." (PMID 25999854, 2015). "This lower efficacy is probably based on the fact that IGF-1 interferes with rather late events in the course of the disease, whereas mini-agrin tackles the structural deficits that are the primary cause of the muscular dystrophy." (PMID 22943509, 2012). "This can be an alternative approach to strengthen myogenesis in addition to previously reported therapeutic strategies against muscular dystrophies, such as stem cell transplantation, the inhibition of myostatin, and IGF-1 supplementation." (PMID 34490258, 2021). "IGF-1 expression activates muscular satellite cells and counteracts muscle function decline in the mouse model of muscular dystrophy." (PMID 28077934, 2017). "LGMD2A patients showed upregulation of the IGF-1 gene as previously observed in other muscular dystrophies." (PMID 19015733, 2008). "While the role of mature mRNA IGF1 molecules, as well as precursor forms of IGF1 protein in physiology (development and aging) as well as pathology (muscular dystrophy, neurological disorders, and cancer), is of key importance, its molecular mechanisms are largely undiscovered." (PMID 32977489, 2020). "Selected genes from this array were validated by immunohistochemistry (IHC) to confirm the presence of IGF-1, BMPR1b and MMP-10 proteins in tibial sections from WT and muscular dystrophy mice." (PMID 31754018, 2020).
sudden sensorineural hearing loss (12 papers, 2010 to 2025). Sensorineural hearing loss which develops suddenly over a period of hours or a few days. "We reported the efficacy of topical IGF1 application for sudden sensorineural hearing loss (SSHL) that is resistant to systemic glucocorticoid treatments in a single arm, non-randomized and open trial." (PMID 25280483, 2014). "IGF‐1 is regarded as a new, promising therapeutic agent for treating sensorineural hearing loss and has undergone clinical trials in patients with idiopathic sudden sensorineural hearing loss that is refractory to systemic steroid therapy." (PMID 37693043, 2023). "Moreover, IGF-1 is crucial for the maintenance of cochlear synapses, and it has been approved for the treatment of human sudden sensorineural hearing loss refractory to corticosteroid treatment." (PMID 36829792, 2023). "Furthermore, our human clinical trial showed the effectiveness of IGF1 hydrogel treatment in patients with idiopathic sudden sensorineural hearing loss that is refractory to glucocorticoid treatment." (PMID 25280483, 2014). "In the field of otorhinolaryngology, gelatin hydrogel containing IGF-1 is clinically applied for the treatment of sudden deafness." (PMID 31660090, 2019). "Intratympanic administration of insulin like growth factor 1 (IGF-1) to treat sudden sensorineural hearing loss shows some promising results, studies of glucosteroids applied that way differ in their significance." (PMID 26042029, 2015). "A clinical trial of recombinant human insulin-like growth factor-1 (IGF-1) in sudden deafness has also been performed, based on the results in animal experiments." (PMID 25278894, 2014). "We randomly assigned patients with sudden deafness refractory to systemic corticosteroids to receive either gelatin hydrogels impregnated with IGF-1 in the middle ear (62 patients) or four intratympanic injections with dexamethasone (Dex; 58 patients)." (PMID 25406953, 2014). "The positive effect of topical IGF-1 application on hearing levels and its favorable safety profile suggest utility for topical IGF-1 therapy in patients with sudden deafness." (PMID 25406953, 2014).
Zinc deficiency (12 papers, 2005 to 2024). A deficiency of the essential metal Zinc; an essential cofactor for many enzymes. "Zinc deficiency results in reduced synthesis and/or secretion of alkaline phosphatase (a zinc enzyme involved in bone metabolism) and growth factors, such as insulin-like growth factor-1 and transforming growth factor-β." (PMID 35698172, 2022). "Intriguingly, zinc deficiency also leads to a decrease in insulin-like growth factor 1 (IGF-1) levels independent from a reduction of total energy intake in rodents and humans." (PMID 25610379, 2014). "In animal models, severe zinc deficiency has been shown to decrease hepatic IGF-1 gene expression and to impair intracellular GH signaling pathway." (PMID 24152751, 2013). "High zinc is inhibitory leading to enhanced IGF-1 signaling whereas zinc deficiency impairs IGF-1 signaling." (PMID 22737083, 2012). "One likely partial explanation for the growth restriction seen in zinc deficiency is the suppression of insulin-like growth factor 1 (IGF-1)." (PMID 22852056, 2012). "One hypothesis suggests that zinc deficiency may reduce the synthesis and secretion of growth hormone (GH) and/or insulin-like growth factor-1 (IGF-1)." (PMID 38542798, 2024). "While zinc deficiency may decrease cancer risk through reducing IGF-1, such a deficient state may increase the activity of aromatase (CYP19), an enzyme required for the conversion of androgens, both testosterone and androstenedione, to estrogens." (PMID 22852056, 2012). "Zinc depletion tests have confirmed that zinc deficiency can result in lower ADG, decreased growth hormone synthesis, and reduced production of IGF-1 induced by growth hormone, thereby impairing the growth of piglets." (PMID 34858378, 2021). "According to research on the effects of zinc shortage on anthropometric measurements, zinc deficiency has an impact on circulating IGF-1 levels regardless of total caloric intake." (PMID 38576864, 2024). "However, maintaining serum IGF-1 levels by exogenous administration or by inducing food intake, or both, in zinc-deficient rats, was not sufficient to correct the growth inhibition induced by zinc deficiency." (PMID 24152751, 2013).
alcohol abuse (11 papers, 2010 to 2025). The use of alcoholic beverages to excess, either on individual occasions ("binge drinking") or as a regular practice. "Due to interest in insulin-based medications for alcohol use disorder, we examined insulin/insulin-like growth factor 1 (IGF-1) genes in the prelimbic (PL) and infralimbic (IL) medial prefrontal cortex, a region linked to alcohol dependence and cognition." (PMID 41400881, 2025). "Moreover, alcohol abuse interferes with insulin-like growth factor-1 (IGF1), a known contributor to pubertal development, so the alcohol delays the time of puberty in both sexes." (PMID 38612922, 2024). "Although stellate cell activation and fibrogenesis are known consequences of chronic alcohol abuse in humans, our results link genetic factors and ethanol-mediated insulin/IGF-1 resistance to severity of steatohepatitis and proneness to develop progressive alcoholic liver disease." (PMID 20814553, 2010). "Thus, the decreased levels of BDNF and IGF-1 in patients with AUD that we observed are in accord with other studies in alcohol, which have reported an association between decreased BDNF levels and alcohol intoxication and between inhibited IGF-1 bioavailability and chronic alcohol abuse." (PMID 29108028, 2017). "However, from the standpoint of therapeutics, a parsimonious approach that globally supports insulin/IGF-1 pathways in the human brain could potentially provide optimum neuroprotection for both neurons and oligodendrocytes in the context of alcohol use disorders." (PMID 29204305, 2017).
Arrhythmia (11 papers, 2011 to 2025). Any cardiac rhythm other than the normal sinus rhythm. "GH and IGF-1 excess are strongly linked to the development of cardiovascular complications including life-threatening arrhythmias, cardiomyopathy, hypertension, atherosclerosis, or valvular heart disease." (PMID 36326330, 2022). "It is possible that reduced secretion of IGF-1 in MSCs within the first few days of enhanced adipogenic signaling, is causally related to the arrhythmia substrates we observed." (PMID 36294819, 2022). "Our results also suggest that maintaining IGF-1 levels early in the progression of ARVC may be beneficial in preventing arrhythmia before structural remodeling occurs." (PMID 36294819, 2022). "Moreover, studies have illustrated that applying MSCs with several factors and substances, for instance, Nestin, Asprosin, IGF-1, and the presentation of cell apoptosis, post-MI arrhythmia." (PMID 34568321, 2021). "Heart disease secondary to the effect of IGF-1 on myocardial tissue generates multiple conditions such as left ventricular hypertrophy (LVH) and the development of arrhythmias, among others." (PMID 39803157, 2024). "Although we show that levels of IGF-1 change as MSCs are exposed to adipogenic conditions and IGF-1 can regulate arrhythmia substrates, we cannot rule out that other growth factors and cytokines are playing a role." (PMID 36294819, 2022). "Additionally, these arrhythmia substrates coincided with a significant reduction in IGF-1 expression in MSCs and were mitigated by IGF-1 treatment." (PMID 36294819, 2022).
astrocytoma (11 papers, 2010 to 2025). "MMP‐9 has been shown to induce IGF‐2/IGFBP2 complex proteolysis resulting in the extracellular release of free IGF‐1 with positive and biological effect on astrocytoma cellular growth and migration." (PMID 29321953, 2018). "One study showed that progesterone can accelerate tumor growth, while another study found a correlation between elevated insulin-like growth factor-1 (IGF-1) levels, which are elevated during pregnancy, and the growth of astrocytoma." (PMID 34828788, 2021).
Barrett esophagus (11 papers, 2012 to 2025). Esophageal lesion lined with columnar metaplastic epithelium which is flat or villiform. "Function-altering polymorphisms in IGF1R as well as IGF1 microsatellite repeats and single strand nucleotide polymorphisms have been shown to affect risk for developing Barrett's esophagus and/or EAC." (PMID 26317790, 2015). "Serum IGF-1 levels in the highest tertile were associated with an increased risk of Barrett's esophagus (adjusted OR 4.05, 95% CI 2.01–8.17) compared with a control group who underwent screening colonoscopy, but were not significantly different from a control group of subjects with GERD." (PMID 23304125, 2012). "Interestingly, subjects with serum insulin and IGF-1 levels in the highest tertiles had the highest risk of Barrett's esophagus." (PMID 23304125, 2012). "These alterations were associated with the down-regulation of the insulin/IGF-1 and ERK signaling pathways, which, in turn, decreased the risk of esophageal adenocarcinoma development." (PMID 37298551, 2023). "In our analysis, we found little evidence for a causal effect of IGF-1 directly on esophageal adenocarcinoma risk, suggesting that the biological mechanism linking IGFBP-1 and esophageal adenocarcinoma risk may be independent of its role regulating IGF-1." (PMID 40987470, 2025). "Calorie restriction reduced glycemia, IGF-1 and the IGF-1/IGFBP3 ratio, and improved insulin sensitivity in patients with Barrett’s esophagus (BE)." (PMID 37298551, 2023). "Alternatively, IGFBP-1 may cause esophageal adenocarcinoma through IGF-1 intercellular transport and intracellular activity, which may not be captured by circulating IGF-1 levels." (PMID 40987470, 2025). "Data from our 24-month randomized trial on patients affected by Barrett’s esophagus suggest that a calorie and protein restriction program together with a specialized supervised approach can affect IGF-1 serum levels, reducing its secretion and also the IGF-1/IGFBP3 ratio." (PMID 34684639, 2021). "Human esophageal adenocarcinoma cell lines such as OE33, but not esophageal squamous cell carcinoma cell lines, showed increased proliferation in response to IGF-1 exposure." (PMID 33513939, 2021).
bone cancer (11 papers, 2015 to 2024). A primary or metastatic malignant neoplasm affecting the bone or articular cartilage. "The present study tried to provide insights into the expression pattern and diagnostic significance of the IGF-1 axis main mediators in three main primary bone tumor types with different degrees of severity." (PMID 36713521, 2022). "The authors of the study thought the elevated bone cancer risk was biologically plausible as bone cancers occur during rapid bone growth of puberty that relate to the insulin-like growth factor 1 (IGF-1) system." (PMID 26064078, 2015). "The simultaneous increase of IGF-1R and its associated mediators in the same set of samples in our current study can confirm the possible role of the IGF-1 axis on the change of ECM proteases in favor of bone cancer cell invasion." (PMID 36713521, 2022). "The ability of the IGF-1 axis to discriminate between bone tumors also malignant and benign tumors was considerable." (PMID 36713521, 2022). "It seemed that the effect of the IGF-1 axis on the expression or activity of extracellular matrix (ECM) components facilitates bone tumor cell promotion." (PMID 36713521, 2022). "Most of the studies in the literature regarding the IGF-1 axis in bone tumor pathogenesis are focused on determining the functional mechanism of this axis." (PMID 36713521, 2022). "Despite several reports on IGF1, Rankl, leptin and the cytokine IL-8, the molecular signaling linking bone marrow adipocyte and bone tumor growth remains to be fully elucidated." (PMID 27049717, 2016). "The association of IGF-1, IGFBP-1, IGFBP-3 and IGF-1R with bone cancer different features." (PMID 36713521, 2022). "As reported, IGF1 levels, sex and growth hormones would reach their maximum during the period of adolescent growth spurt and puberty, which might contribute to the development of bone tumors." (PMID 26371026, 2015). "The current study is designed to shed more light on the expression profile of the IGF-1 axis in predominant bone tumor types and to underscore the status of IGF-1, its receptor, and major binding proteins in bone tumor severity." (PMID 36713521, 2022).
central precocious puberty (11 papers, 2017 to 2025). "For instance, KL regulates growth hormone (GH) secretion from the pituitary gland and is associated with growth factor 1 (IGF-1) and rapid-onset central precocious puberty (RP-CPP), which may be relevant for female precocious puberty." (PMID 39519156, 2024). "Previous studies on central precocious puberty indicated that IGF-1 levels were positively correlated with LH levels, but not with sex steroid hormone." (PMID 36425849, 2022). "In children with hCG-induced precocious puberty, IGF-1 or IGFBP-3 levels present a heterogeneity and commonly vary within an age-matched reference." (PMID 36425849, 2022). "Patients with hCG-induced precocious puberty would have age-matched IGF-1 or IGFBP-3 levels after regression of precocious puberty." (PMID 36425849, 2022). "IGF-1 levels in patients with human-chorionic-gonadotropin-induced precocious puberty have heterogeneity, but IGF-1 standard deviations are mostly within the normal range." (PMID 36425849, 2022). "Taken together, all of these reports show a strong association of sexual precocity with the PAPP-A and PAPP-A2 genes via IGF-1." (PMID 29293544, 2018). "Third, the most probable connection between adrenal and gonadal maturation is insulin–IGF-1 axis, as increased concentrations of IGF-1 and insulin have been associated with both PA and central precocious puberty." (PMID 29163361, 2017). "Young children may however also present with central precocious puberty or increased IGF-1 concentrations." (PMID 40746184, 2025). "Our study aimed to evaluate the IGF1 and IGF1-SDS profiles in children with precocious puberty compared with controls to determine their potential as diagnostic markers for CPP, particularly in differentiating progressive forms from incomplete or nonprogressive forms." (PMID 40555852, 2025). "Recent studies suggest a link between the Klotho protein, sex hormones, and insulin-like growth factor-1 (IGF-1), indicating that α-Klotho levels may rise during puberty, including in central precocious puberty (CPP) cases." (PMID 38650713, 2024). "IGF-1 and IGFBP-3 levels in patients with hCG-induced precocious puberty were analysed and compared during the therapy for hCG-secreting tumors." (PMID 36425849, 2022). "Furthermore, IGF-1 and IGFBP-3 levels in children with precocious puberty were significantly higher than those in normal children of the same age and sex." (PMID 38356806, 2024).